STAT3 (signal transducer and activator of transcription 3)
Diseases named in the same sentence as STAT3 in open-access papers (continued):
Sharing a sentence is not in itself a finding about the gene and the disease.
tumor (continued). "It suggests that sialidase can sensitize tumor myeloid cells to STAT3 inhibition, and dramatically enhance the anti-tumor effect of STAT3 targeted therapy." (PMID 33224886, 2020). "Inhibiting the IL-6/STAT3 signaling pathway correspondingly shifts macrophages to the M1 polarization phenotype, and blocking the IL-6/STAT3 signaling pathway can dramatically reduce tumor formation." (PMID 32904108, 2020). "Over-activation of STAT3 pathway increases cell-cycle progression, tumor invasion, angiogenesis, metastatic spread and suppress apoptosis." (PMID 33121520, 2020). "IL-6 activates STAT3 phosphorylation, inducing the transcription of genes that regulate tumor cell proliferation and antiapoptosis." (PMID 32742470, 2020). "In the current study, H19 expression was positively correlated with activation of STAT3 signaling in PC cells, which has been reported to be involved in tumor initiation, stemness maintenance and chemotherapy resistance 22-24." (PMID 32626524, 2020). "In the present investigation, we demonstrated initially that HCC patients with overexpression of p-STAT3 in tumor tissues suffered from unfavorable survival after TACE." (PMID 31942180, 2020). "STAT3 stimulates oncogenesis by promoting cell proliferation, inhibiting apoptosis, suppressing anti-tumor immune response, and dysregulating the cell cycle, survival, and senescence." (PMID 32971907, 2020). "CD8+ T cell infiltration in advanced-stage tumor was systematically inhibited by Th17 cells via IL-17A/STAT3/CXCR3 axis." (PMID 32503584, 2020). "Within this article, we will discuss the role of STAT3 in NSCLC regarding its tumor cell-intrinsic and extrinsic mechanisms." (PMID 32365499, 2020). "Inhibition of NFATc2 substantially decreased the expression of proinflammatory cytokines, followed by impaired STAT3 activation and suppressed xenograft tumor growth." (PMID 32041943, 2020). "We further demonstrate that during the later stages of tumor development in Nod2−/− mice, STAT3 and ERK are activated, and there are increased numbers of neutrophils, inflammatory monocytes, and CD4+ T cells in the blood and liver." (PMID 33239685, 2020). "We propose that the tumor suppressor function of STAT3 is likely attributable to the heterochromatin-promoting activity of uSTAT3 in the non-canonical JAK/STAT pathway." (PMID 32087696, 2020). "These interacted with macrophages in a HPSE-mediated manner to maintain a chronic inflammatory condition, which aided the formation of a tumour-promoting microenvironment with NF-κB signalling and induction of STAT3 expression." (PMID 33256730, 2020). "Interaction between NFKB and STAT3 is a key mediator of crosstalk in the tumor inflammatory microenvironment." (PMID 32883235, 2020). "In the present study, we revealed that epimedokoreanin B significantly inhibited STAT3 activation in human macrophages and tumor cells and suppressed macrophage polarization to the M2 phenotype." (PMID 32256354, 2020). "STAT3 has a strong role supporting tumor progression and therefore, significant efforts have been aimed at the development of specific and non-toxic inhibitors for cancer treatment." (PMID 32083000, 2020). "It is widely accepted that STAT3 regulates a variety of cellular processes, such as tumor cell growth, survival, invasion, cancer stem cell-like characteristic, angiogenesis and drug-resistance." (PMID 31949487, 2020). "In particular, STAT3 hyperactivation in tumor cells has a vital role in dendritic cells (DCs) maturation." (PMID 32972405, 2020). "IL-6/JAK2/STAT3 signaling can down-modulate the antitumor immunity of tumor-infiltrating immune cells because STAT3 negatively regulates the functions of neutrophils, natural killer (NK) cells, effector T cells, and dendritic cells." (PMID 32883032, 2020). "The deregulated activity of STAT3 in cancer cells as well as in GSCs makes it a very promising therapeutic target for the development of an effective strategy for a complete tumour eradication." (PMID 32486489, 2020).
tumor (continued). "Abnormal activation of the STAT3 pathway leads to tumor cell apoptosis and an imbalance of cell proliferation." (PMID 33082817, 2020). "Treatment with antisense oligonucleotides resulted in decreased STAT3-dependent gene expression is several cancer cell lines; furthermore, inhibition of tumour growth was observed in mouse xenografts of prostate." (PMID 32899142, 2020). "In preclinical in vitro and in vivo models of cisplatin-resistant NSCLC, with increased JAK2 and STAT3 activation levels, the addition of ruxolitinib to cisplatin decreased STAT3 activation and cell growth, enhanced apoptosis, and inhibited tumor growth." (PMID 33521321, 2020). "We previously reported tumor regression and inhibition of STAT3 signaling in HNSCC xenografts after intravenous administration of STAT3 decoy (5 mg/kg/day), 5 days per week for 2 weeks." (PMID 33206698, 2020). "According to recent studies, aberrantly activated STAT3 signaling is considered a paradigm for tumor initiation and malignancy, radiochemoresistance, and recurrence due to observation in many types of cancers." (PMID 32183406, 2020). "We further assessed STING and downstream PD-L1 and p-Stat3, as well as tumor-infiltrating immune cells by performing IHC." (PMID 33288772, 2020). "In pancreatic cancer, a blockade of LIF:LIFR:STAT3 signaling resulted in a decrease in the expression of CSC-associated markers (CD133, CD24, and CD44), a reduction in tumor initiation and formation, and an overall less aggressive phenotype." (PMID 32023849, 2020). "Recently, some scientists found that Sunitinib was also an immune-modulator, potently reversing tumor MDSC accumulation through STAT3 or C-Kit signal." (PMID 33613512, 2020). "Hyperactivated STAT3 in tumor cells can suppress the expression of IL-12 and TNF-α, leading to a decrease in Bcl-2 expression in DCs." (PMID 32972405, 2020). "At the molecular level, both CD44 and STAT3 have been reported to support tumor angiogenesis in several tumor models." (PMID 33335857, 2020). "Given its fundamental role in tumor proliferation and progression, STAT3 has emerged as a promising target for cancer treatment, especially in GC therapy." (PMID 32576206, 2020). "In tumor cells, STAT3 often interacts with other signaling pathways, such as NF-κB, to confer robustness for tumor progression." (PMID 32972405, 2020). "Activation of STAT3 has been shown to drive downstream gene transcription, and its gene products subsequently promote tumor development and progression." (PMID 33505963, 2020). "It was noted that in the KrasG12D model, the massive activation of the STAT3 pathway, which led to tumour progression, was induced by tumour-infiltrating myeloid cells, which stimulated the neoplastic cells via IL-6 trans-signalling." (PMID 32864098, 2020). "Curcumin worked synchronously with EGCG and considerably interfered with tumor conditioned media-induced transition of normal endothelial cells toward tumor endothelial cells by inhibition of the JAK/STAT3 signaling pathway." (PMID 32290543, 2020). "Epimedokoreanin B showed an inhibitory effect on STAT3 activation in both macrophages and tumor cells, and epimedokoreanin B suppressed tumor progression in the LM8 tumor-bearing mouse model in the present study." (PMID 32256354, 2020). "To confirm the clinical relevance of HIF‐1α and STAT3 interaction, we collected 20 tumour samples from TNBC patients." (PMID 32065498, 2020). "Following that, impeding the expression of STAT3 by some small molecules attributed to decreasing the infiltration of Tregs the tumor microenvironment." (PMID 32486001, 2020). "Functional experiments show that p140Cap negatively regulates Src and STAT3 signaling, affects anchorage-independent growth and migration, in vivo tumor growth and spontaneous lung metastasis formation." (PMID 31285546, 2020).
tumor (continued). "STAT3 activation is a common feature of tumour cells within the tumour stroma, and it is thought to prevent cell apoptosis and enhance tumour cell growth and metastasis." (PMID 33037771, 2020). "MSC pre-treated with cisplatin increased CCL5 expression and phosphorylation of tyrosine kinases (PLC, WNK1, c-Jun, STAT3), possibly playing roles in tumor cell changes, as witnessed in breast cancer cells." (PMID 32499779, 2020). "By suppressing STAT3 phosphorylation, STAT3 activation is reduced, IL-6 production decreases, thus inhibiting tumor growth and ovarian metastases." (PMID 33536913, 2020). "STAT3 activation confers high Programmed death-ligand (PD-L) expression, which promotes tumor immune evasion." (PMID 33096674, 2020). "It has been demonstrated that the over-activation of STAT3 results in tumor invasiveness by matrix metallopeptidase secretion and the upregulation of the focal adhesion kinase (FAK)." (PMID 32823915, 2020). "Acetylcholine and its analogue bind to α5‐nAChR on the cell surface and activate p‐Stat3, which subsequently activates the expression of Jab1 to promote tumour cell EMT and metastasis." (PMID 31930655, 2020). "Inactivation of these phosphatases by either genetic mutations or epigenetic regulation leads to chronic activation of STAT3 phosphorylation in tumor cells." (PMID 33182552, 2020). "NF-κB/STAT3 signaling is thought to play an important role in tumor proliferation, progression, and chemoresistance in CRC18." (PMID 32581212, 2020). "HMGA1 induces STAT3 expression that has a main role in inflammation, malignant transformation, and tumor progression; STAT3 overexpression also leads to hematologic malignancies." (PMID 32503270, 2020). "Expression of GPR81 in tumor cells can be regulated through an autocrine feedback loop of lactate by the induction of Signal transducer and activator of transcription 3 (STAT3) that directly binds to the GPR81 promoter to induce its expression." (PMID 33324565, 2020). "IL-6 is a pro-inflammatory cytokine produced in tumor cells and activates the STAT3 pathway through binding to the IL-6 receptor." (PMID 32150979, 2020). "Blocking STAT3 activation by expressing STAT3β in the tumors increased tumor-infiltrating NK cells and attenuated LPS-induced NK cell reduction." (PMID 32312954, 2020). "TAMs polarize towards M2 type through the IL-6/STAT3 signaling pathway to promote tumor metastasis and rejects immune cells from penetrating." (PMID 33537237, 2020). "They demonstrate that STAT3 signaling is blocked when Prx2-dependent STAT3 oxidation is not counterbalanced by the Trx/TrxR/NADPH system, leading to the death of tumor cells that depend on STAT3 signaling." (PMID 32908147, 2020). "Enhances radiation-induced apoptosis by inhibiting STAT3; it also downregulates Mcl-1, cyclin D1 and survivin expression, overcomes resistance to radiation in cells and suppresses tumor growth in vivo." (PMID 32872659, 2020). "To further elucidate the effect of EHD on the STAT3/cyclin D1 signalling pathway, we analysed the STAT3 and cyclin D1 levels in xenograft tumours in nude mice by immunohistochemistry analyses." (PMID 32382281, 2020). "In vivo, administration of STAT3 inhibitor pacritinib reduced tumor size in a mouse model bearing LN18 cells co-cultured with TAMs exosomes." (PMID 32178454, 2020). "Meanwhile, immune cells infiltrating the tumor produce cytokines, activating key transcription factors (NF-κB, STAT3, and AP-1), and participate in tumor progression and angiogenesis." (PMID 32499779, 2020). "Many reports in the literature describe the role of JAK/STAT3 signaling in gene expression reprogramming that bears epithelial–mesenchymal transition regulating tumor metastasis, the transition of cancer stem cells and chemoresistance." (PMID 32756477, 2020). "These cells secrete pro-tumorigenic cytokines and growth factors to amplify STAT3 activation within the tumor cells, resulting in tumor growth." (PMID 32365499, 2020).
tumor (continued). "Cell proliferation pathways mediated by c-Myc, cyclin D1 and STAT3 can promote unrestrained GSK3β-dependent tumor cell proliferation." (PMID 32503133, 2020). "The activation of NFκB and STAT3, as a result of hypoxia in the tumor niche, can also induce expression and release of CCL2 from CAFs." (PMID 33363032, 2020). "STAT3 is also required for the recruitment of stromal and immune cells to the tumor microenvironment to facilitate tumor progression." (PMID 33279931, 2020). "This study now expands on the potential therapeutic benefits of this small molecule by showing that GL can harness the main bulk of tumor cells as well as the tumor-initiating stem cell niche in which activation of STAT3 is clearly demonstrated." (PMID 32811873, 2020). "We simultaneously analyzed the phosphorylation/activated state of STAT3, Akt, Erk1/2, and p38 in the distal colon and tumor tissues from IRF3+/+, IRF3–/–, IRF3fl/fl, and IRF3fl/flVillincre mice following AOM/DSS treatment." (PMID 33188184, 2020). "In ALK+ tumor cells, activation of the STAT3 driven by NPM-ALK fusion protein results in the increased expression of PD-L1." (PMID 33292562, 2020). "Inhibition of Activation of STAT3 can provide growth inhibition and induction of apoptosis in tumor cells." (PMID 33536913, 2020). "In oral squamous cell carcinoma (OSCC) cells, miR-144-3p can exert a tumor suppressive function by directly targeting the ERO1L/STAT3 pathway to affect OSCC treatment." (PMID 33046994, 2020). "When treated with mAb targeting IL-6, these mice harbored fewer and smaller lung lesions, less evident lung surface neoplasms, a prominent 46% reduction in the proliferation of tumor cells, and a downregulation of Stat3 activation." (PMID 32117295, 2020). "After that, the transcription of related genes for fatty acid β-oxidation is activated by phosphorylated STAT3, and β-oxidation leads to procarcinogenic macrophage M2 polarization, promoting tumorigenesis and tumor progression." (PMID 32908642, 2020). "Further, siRNA administration against STAT3 in the xenograft model demonstrated a decrease in tumor volume and induction of apoptosis." (PMID 33344262, 2020). "IL-6, an activator of STAT3, frequently elevated in RCC, is known to induce tumor progression and metastasis across tumor types, and is sufficient to induce skeletal muscle STAT3 activation leading to muscle wasting resulting cachexia." (PMID 32560494, 2020). "In this study, EHD not only slowed tumour growth in LC mice with PCBS syndrome but also regulated the STAT3/cyclin D1 signalling pathway." (PMID 32382281, 2020). "Further, IL-6 triggers the activation of the IL-6/JAK/STAT3 pathway which generally enhances proliferation, survival, invasiveness and metastasis of tumor cells, while strongly suppressing the antitumor immune response." (PMID 32899119, 2020). "CAFs can induce hepcidin in tumor cells through interleukin 6 (IL-6) secretion and stimulation of signal transducer and activator of transcription 3 (STAT3) signaling, illustrating one of the mechanisms where iron metabolism underpins tumor-stroma crosstalk." (PMID 32328462, 2020). "It has been shown to function as a tumor suppressor by targeting signal transducer and activator of transcription 3 (STAT3) and several other downstream effectors of the KRAS and nuclear factor-kappa B (NF-kB) pathways, often together with miR-23b." (PMID 33266470, 2020). "STAT3 inhibition in the myeloid compartment displays a remarkable induction of the T cell anti-tumor capabilities and promotes their expansion in vivo." (PMID 32150944, 2020). "It is worth mentioning that, to date, most of the anti-tumor drugs applied in the treatment of GC cells by targeting STAT3 have been isolated from plants." (PMID 32545648, 2020). "Together with STAT5, STAT3 stabilizes Foxp3 expression in response to IL-2; IL-23-driven STAT3 activation in tumor-infiltrating Treg cells achieves the same phenotype." (PMID 33143070, 2020).
tumor (continued). "Several studies have demonstrated that STAT-3 is aberrantly activated and plays a crucial role in tumor initiation and progression in many cancers, including STS." (PMID 32998376, 2020). "Resveratrol lowers tumorigenic potential and improves the effects of radiotherapy in vitro and in vivo against GBM-derived tumor stem cells to by inhibiting the signal transducer and activator of transcription 3 (STAT3)." (PMID 32075265, 2020). "The pronounced desmoplasia triggers β1-integrin mechanosignalling that promotes tumour progression through STAT3 activation." (PMID 33037194, 2020). "In summary, our data showed an association of IL21+ and IL26+ immune cell infiltration, increased ADC, and aggressive tumor disease, most likely due to the activation of the key cancer signaling pathways ERK1/2 and STAT3 and formation of tumor colonies." (PMID 31948053, 2020). "They observed that miR-103a downregulates tumor suppressor gene (PTEN) in macrophages which in turn activated AKT/STAT3 pathways as well as multiple angiogenic, immunosuppressive, and tumor-promoting factors." (PMID 32992449, 2020). "According to previous research, SEZ6L2 has been shown to be regulated by transcription factors, such as STAT3, which upregulate the expression of the vascular endothelial growth factor and promote tumor angiogenesis and cancer progression." (PMID 32148567, 2020). "IL-1β is known to act as an inhibitor of tumor apoptosis via the induction of signal transducer and activator of transcription 3 (STAT3)." (PMID 32069807, 2020). "ViscumTT treatment, a whole mistletoe extract, significantly reduced tumor growth in ES cells in vivo through the JAK/STAT3 pathway and its downstream targets, including BIRC5 and Myc." (PMID 32754598, 2020). "STAT3 inhibition impaired tumor growth, increased anti-tumor T cell responses and decreased the accumulation of myeloid cells in the spleen." (PMID 33330068, 2020). "It is reported that IL-6-mediated JAK/STAT3 pathway plays an important role in tumor proliferation, invasion and metastasis." (PMID 33153467, 2020). "Although STAT3 is considered to be crucial to regulate the immune response in the tumor microenvironment, few studies have systematically reported the impact of STAT3 in different immune cells." (PMID 32486001, 2020). "The western blotting results showed that protein levels of p-JAK2 and p-STAT3 decreased significantly in NaB group in both tumor (T) and normal peritumoral (N) tissues (p < 0.001)." (PMID 32518521, 2020). "In return, elevated IL6 in cell supernatants induces EMT, and the invasion and metastasis of tumor cells via signal transducer and activator of transcription 3 (STAT3) signaling." (PMID 32308766, 2020). "The tyrosine kinase receptor antagonist ruxolitinib can inhibit JAK and prevent STAT-3 activation and thus inhibit tumor growth and increase apoptosis of tumor cells." (PMID 32466266, 2020). "Subsequent investigations further confirmed a tumor suppressive role for STAT3 in K-RAS-driven lung tumorigenesis." (PMID 32365499, 2020). "Signal Transducers and Activators of Transcription 3 (STAT3), one of the most important intracellular transcription factors, is reported to be constitutively activated in most tumor types." (PMID 32733808, 2020). "Mechanistically, tumor-secreted factors and GM-CSF + IL-6 signaling activates Stat3 and Cebpβ leading to the expression of miR-21a, miR-21b, and miR-181b." (PMID 33133086, 2020). "Taken together, these results demonstrate that JAK2/STAT3 signalling participates in OCA‐mediated tumour inhibition." (PMID 33164339, 2020). "Specifically, STAT3 participates in tumor initiation, metastasis, and resistance to anti-tumor therapies." (PMID 32604771, 2020). "It is found that inhibiting the expression of STAT3 reprograms TAMs into M1 macrophages to inhibit tumor growth." (PMID 33224886, 2020).